CAV1 (caveolin 1)
Diseases named in the same sentence as CAV1 in open-access papers (continued):
Sharing a sentence is not in itself a finding about the gene and the disease.
tumor (continued). "We then tested the consequences of mutating S80 in CAV1 in its tumor suppressor activity and its relation to ER stress signaling." (PMID 32811828, 2020). "Alternatively, CAV1 has recently been implicated as a core component of the calcium-dependent apoptotic pathway that regulates critical mitochondrial functions during tumor development." (PMID 32811828, 2020). "The loss of stromal CAV1 has been reported to bring about activation of the tumor microenvironment, and induce the transformation of fibroblasts into CAFs." (PMID 32401768, 2020). "The univariate Cox regression model revealed that age, race, histologic grade, anatomic subdivision, venous invasion, residual tumor, clinical stage, expression of CAV1 and ATG4C mRNA were associated with prognosis of EOC patients in terms of OS (P<0.05)." (PMID 32401768, 2020). "Previous work from our group linked CAV1-mediated tumor suppression in the presence of E-cadherin to the inhibition of β-catenin/TCF-LEF-mediated transcription of survivin and COX-2." (PMID 32825247, 2020). "CAV1-deficient EC and the respective blood vessels were further characterized by a less stabilized, pro-angiogenic phenotype that facilitated tumor growth." (PMID 32273493, 2020). "The tumor suppressor activity of CAV1 has been associated with its scaffolding domain (CSD), which is implicated in binding to and inhibiting the activity of numerous signaling proteins." (PMID 32811828, 2020). "As a consequence, the tumor growth-promoting feature of Cav-1-deficient PSCs is reversed through suppressing shh signaling with cyclopamine and by interfering with Gli-1 in Aspc-1 cells." (PMID 32377291, 2020). "In cancer-associated fibroblasts, Cav-1 underlies matrix stiffness and favors tumor invasion and metastasis, whereas others have shown that its loss in fibroblasts correlates with poor prognosis." (PMID 32377291, 2020). "Here we report for the first time, that the tumor suppressor activity of CAV1 is linked to the repression of the ability of cells to engage adaptive programs to cope with ER stress." (PMID 32811828, 2020). "Caveolin-1 (CAV1), is a broadly expressed, membrane-associated scaffolding protein that acts both, as a tumor suppressor and a promoter of metastasis, depending on the type of cancer and stage." (PMID 32811828, 2020). "Here, we reveal that tumor growth seen in coinjected Aspc-1 cells and Cav-1-silenced PSCs seems to be well associated with differences in their microvascular density." (PMID 32377291, 2020). "Remarkably, the introduction of the single S80A mutation fully abrogated the capacity of CAV1 to suppress tumor formation in vivo in B16F10 cells." (PMID 32811828, 2020). "Even more important, these CAV1-deficient tumor ECs were more sensitive to RT and promoted an improved tumor RT response." (PMID 32273493, 2020). "In terms of the signaling pathways implicated in CAV1-associated tumor suppression, there are several studies on its role as a plasma membrane-bounded protein (see Section 1)." (PMID 32458269, 2020). "On the other hand, the re-expression of CAV1, often observed in later stages of cancer, has been linked to tumor progression, multi-drug resistance, and metastasis." (PMID 32458269, 2020). "In fact, results from different laboratories reported that in breast context CAV1 loss promotes tumor growth and metastasis." (PMID 32825330, 2020). "A large number of reports support the role of CAV1 as a tumor suppressor, associating the reduced expression of CAV1 with cell transformation." (PMID 32458269, 2020). "Previous results from our group linked the tumor suppressor role of CAV1 to its ability to suppress β-catenin/Tcf-Lef-dependent transcription of genes including survivin and COX2 in an E-cadherin-dependent manner." (PMID 32811828, 2020).
tumor (continued). "The proposed mechanism involves tumor cell stimulation of oxidative stress among adjacent fibroblasts, leading to downregulation of caveolin-1 (CAV1)—a plasma membrane protein associated with increased mitochondrial activity." (PMID 33108391, 2020). "Data on the CAV1-dependent epithelia-stroma crosstalk indicates that stromal CAV1 possesses tumour-suppressor properties, whereas loss of stromal CAV1 fosters malignant epithelial cell resistance by evading apoptosis." (PMID 30871022, 2019). "Utilization of lactate has also been described in tumor-associated fibroblasts, which have low expression of CAV-1, an inhibitor of myofibroblast differentiation." (PMID 31788448, 2019). "Data on the stroma-tumor crosstalk indicated that caveolin-1 (CAV1) and breast cancer type 1 susceptibility protein (BRCA1) involved in oxidative stress pathway in CAFs." (PMID 31014370, 2019). "This decrease in CAV-1 expression in tumor tissue suggests that loss of CAV-1 is required for the disease to establish which relates to clinical outcome." (PMID 31889941, 2019). "Current research on CAV1 indicates that CAV1 can regulate multiple cancer-associated biological processes that include tumorigenesis, tumor growth, cell migration and metastasis, cell death and survival, and multidrug resistance." (PMID 31296840, 2019). "Further on, TRIAP1-expressing stromal fibroblasts mediate radiation resistance in vivo when respective cells are co-implanted with CAV1-deficient PC3 tumour cells." (PMID 30871022, 2019). "Several studies have reported that Cav-1 plays a tumor-suppressive role, while others have revealed that increased expression of Cav-1 is implicated in tumor progression and metastasis." (PMID 31297035, 2019). "Integrins are stimulators of cancer cell proliferation and tumor angiogenesis linked to the Ras-ERK pathway by CAV-1, tyrosine kinase Fyn and Shc and integrin alpha-1 expression is directly regulated by oncogenic factor c-MYC." (PMID 31889941, 2019). "Mechanically, cancer cells induce the activity of autophagy in CAFs through the loss of Cav-1, promoting oxidative stress in adjacent stromal fibroblasts, and subsequently resulting in promoting tumor growth." (PMID 31759347, 2019). "Cav-1 is the main component of plasma membrane invaginations (calveolae), and deregulation of tumor Cav-1 is highly implicated in BC." (PMID 31783552, 2019). "A loss of caveolin-1 in fibroblasts induces a CAF phenotype in the tumor microenvironment and drives the constitutive activation of several oncogenes, such as c-Myc, v-Abl, v-Src, H-Ras, and Neu/ErB2 in stromal fibroblasts." (PMID 31591367, 2019). "In early stages of disease, CAV1 is proposed to function predominantly as a tumor suppressor, whereas at later stages, CAV1 expression is linked more to tumor progression and metastasis." (PMID 31362353, 2019). "Specifically, we have shown that tumor suppression by CAV1 is linked to the expression of E-cadherin." (PMID 31362353, 2019). "Decreased expression of CAV1, another component of caveolae within the tumor microenvironment, is also consistently associated with poor clinical outcomes in patients with a wide variety of malignancies." (PMID 31067787, 2019). "As the aberrant expression of E-cadherin is a hallmark of EMT and is associated with poor clinical outcome in PCa6, we set out to study the association of CAV1 and E-cadherin expression in human PCa tumours." (PMID 29402961, 2018). "This relationship is thought to occur via oxidative stress in the cancer associated stroma (CAS), driven by tumor cell generation of reactive oxygen species and stromal cell loss of caveolin-1 (CAV1), an inhibitor of nitric oxide production." (PMID 30211120, 2018). "Higher tumor Cav-1 levels and lower stromal Cav-1 levels were significantly associated with longer PFS of nab-paclitaxel and gemcitabine." (PMID 30348118, 2018).
tumor (continued). "Cav-1 deficient fibroblasts upregulate glycolytic enzymes and secrete energy rich metabolites which can be used by the proliferating tumour cell in the so called ‘reverse Warburg effect’." (PMID 29416729, 2018). "The relationship between CAV1, oxidative stress, and inflammation has been best studied in the tumor microenvironment, where loss of CAV1 was reported to lead to oxidative stress and to drive inflammation." (PMID 30246033, 2018). "In agreement with this, our previous results suggest that metformin treatment of cultured breast cancer cells inhibits their ability to induce loss of CAV1 (a marker of tumor-stromal metabolic coupling) in co-cultured fibroblasts." (PMID 30211120, 2018). "The expression of caveolin-1 (CAV1) in both tumor cell and cancer-associated fibroblasts (CAFs) has been found to correlate with tumor aggressiveness in different epithelial tumor entities, whereas less is known for caveolin-2 (CAV2)." (PMID 29850392, 2018). "Mechanistically, these pro-invasive effects were found to be driven by caveolin-1, a lipid raft protein implicated in various aspects of tumour progression including EMT." (PMID 29331414, 2018). "The tumour-promoting role of CAV1 is associated both with resistance to apoptosis and increased cancer cell migration or invasion." (PMID 29402961, 2018). "All these studies documented that loss of stromal CAV1 expression or weak expression is a regulatory key in all aspects of tumorigenesis and tumour progression." (PMID 28515480, 2017). "We further demonstrated for the first time that the decreased radiation-induced growth delay of tumors with co-implanted Cav1-silenced HS5 cells was associated with an increased reactive tumor stroma." (PMID 28112237, 2017). "Cav-1 acts as a positive or negative regulator of tumor cell growth via the reciprocal control for the RAF-ERK feedback loop, and the mitogenic switch of Cav-1 function is tightly linked to bidirectional alteration of its expression in tumor progression." (PMID 29141593, 2017). "It is becoming clear that altered expression of Cav-1 in tumor stroma, particularly in cancer-associated fibroblasts (CAFs), is linked to the malignant progression of various types of human cancers." (PMID 29141593, 2017). "The scaffold protein caveolin-1 (CAV1), a principal component of caveolar membrane coat, regulates multiple cancer-associated processes, including cellular transformation, tumor growth and survival, cell migration and metastasis, and multidrug resistance." (PMID 29097801, 2017). "At the level of the primary site, clodronate-liposome treatment caused equal tumor growth and weight reduction in both WT→WT and Cav1 KO→WT chimeras." (PMID 29212030, 2017). "Although Cav1 has been shown to inhibit microvascular permeability and has been considered as a tumor-suppressor for years, the underlying cellular mechanism has yet to be discovered." (PMID 29100301, 2017). "Loss of stromal CAV1 expression has been characterised as a key regulator in the development of the “reverse Warburg effect” and “the autophagic tumour stroma model of cancer metabolism”13–15." (PMID 28515480, 2017). "Despite a growing body of evidence on Cav-1 implication in tumorigenesis, its role in tumor growth and underlying molecular mechanisms remain largely undefined." (PMID 29141593, 2017). "Cav-1 is generally regarded as a tumor suppressor, and studies have implicated loss of Cav-1 in the pathogenesis and progression of multiple human cancers." (PMID 28546853, 2017). "In Woodman’s paper, B16F10 tumor cells were transplanted subcutaneously into WT and Cav-1-deficient mice." (PMID 29250058, 2017). "A study showed that loss of CAFs Cav-1 promotes tumor microenvironment remodeling and tumor development." (PMID 29141593, 2017). "First of all, oxidative stress related loss of stromal caveolin-1 (Cav-1) seems one of the most important predictive biomarkers of tumor recurrence, invasion and prognosis." (PMID 28915713, 2017).
tumor (continued). "In this context, cancer-associated fibroblasts that express reduced levels of caveolin-1 serve as tumor cell-interacting stromal cells." (PMID 28257096, 2017). "While the precise mechanism is still not well understood, loss of CAV1 has been observed to lead to increased oxidative stress, activation of HIF1α and the induction of aerobic glycolysis/the Warburg effect in the tumor microenvironment." (PMID 28067804, 2017). "Our results suggested that rs3807987 polymorphism in CAV-1 was associated with tumor size and PR status while rs7804372 polymorphism was linked to ER and Her-2 status." (PMID 29207674, 2017). "The increased radiation resistance was associated with increasing amounts of reactive tumor stroma and a Cav1 re-expression in the malignant epithelial cells." (PMID 28112237, 2017). "Currently, great attention has been attracted in the study of the association of Cav-1 to tumor development and metastasis." (PMID 26919102, 2016). "In fact, exosomes are suggested as a nanodelivery system, which functions for tumour-associated proteins and, consequently, Cav-1-bearing exosomes." (PMID 25502465, 2016). "In multivariate Cox regression analysis including the known prognostic marker GS and local tumour stage, low tumor Cav-1 was significantly associated with poor prognosis and gave additional prognostic information." (PMID 27764093, 2016). "Subsequent study showed that loss of Cav-1 in mesenchymal stromal cells led to increased aerobic glycolysis and inflammation in the tumor stromal microenvironment via activation of HIF and NFkB." (PMID 26828520, 2016). "Downregulation or loss of function in CAV1 has previously been documented as a determinant of aggressiveness in GBM tumor growth." (PMID 27124395, 2016). "In advanced stages of this disease, CAV1 expression in tumor cells is associated with enhanced metastatic potential, while, at earlier stages, CAV1 functions as a tumor suppressor." (PMID 27259249, 2016). "Increased tumor growth on Cav1-deficient mice was linked to decreased integration of smooth muscle cells into the wall of newly formed blood vessels and thus with a less stabilized vessel phenotype compared with tumors from Cav1 wild-type animals." (PMID 25985209, 2015). "The authors also reported these effects can be reduced by RAPA and suggested the involvement of the stromal mTOR pathway on blood vessel formation and tumor growth in Caveolin-1–deficient tumors." (PMID 26098779, 2015). "Cav1 regulates therefore multiple cancer-associated processes including cellular transformation, tumor growth, cell migration and metastasis, cell death and survival, multidrug resistance and angiogenesis." (PMID 26474461, 2015). "Our data from a significantly larger clinical dataset similarly demonstrates Cav-1 to be associated with worse tumor histologic grade and clinical outcomes." (PMID 26065715, 2015). "Cav-1 has been proved to modulate multiple cancer-associated processes including cellular transformation, tumor growth, cell migration and metastasis, cell death and survival, multidrug resistance and angiogenesis in a number of signaling pathways." (PMID 26066055, 2015). "Due to the substantial effects of Cav-1 loss on tumor initiation and growth rate, we were unable to independently assess the effects of Cav-1 levels on chemotherapy or radiation response using these cell line models." (PMID 26065715, 2015). "Tumors implanted into Cav1-deficient mice showed a significantly increased tumor growth when compared with the tumors grown in the wild-type controls." (PMID 25985209, 2015). "Increased radiation-induced tumor growth delay in Cav1-deficient mice was associated with an increased endothelial cell apoptosis." (PMID 25985209, 2015).
tumor (continued). "In order to better define a mechanism for how Cav-1 loss attenuates tumor cell growth, we performed comprehensive immunoblotting of various signaling pathways in our isogenically matched MIA-PaCa2 and BxPC3 cells." (PMID 26065715, 2015). "Since stromal loss of Cav-1 is a marker of aging and stress in the tumor microenvironment, it can be anticipated that Cav-1 can be used as biomarker for therapeutic stratification when treating tumors with rapamycin or other mTOR inhibitors." (PMID 26284191, 2015). "In contrast, the levels of tumor hypoxia and proliferation were more similar in Cav1-deficient and wild-type mice after irradiation." (PMID 25985209, 2015). "Ultrastructural analysis revealed an irregular lining of smooth muscle cells and the presence of fenestrae in angiogenic ECs from tumors of Cav1-deficient animals, thereby corroborating the less mature and functional inferior phenotype of these tumor vessels." (PMID 25985209, 2015). "Up-regulation of Cav1 is associated with metastatic disease progression of various cancers and appears therefore as a good promoter of tumor dissemination." (PMID 26474461, 2015). "In this context, rapamycin significantly decreased the stromal content in Cav-1-deficient CAFs and inhibited tumor growth." (PMID 26284191, 2015). "In Cav1-deficient animals these tumor vessels were smaller in size and showed an impaired morphology after irradiation accompanied by increased areas of necrosis close to the affected angiogeneic vessels." (PMID 25985209, 2015). "Caveolin-1 (CAV1) has been implicated both in tumor suppression and progression, whereby the specific role appears to be context dependent." (PMID 26054531, 2015). "For this, subcutaneous MPR31-4 prostate xenografts were implanted into Cav1-deficient mice and their wild-type littermates and were irradiated locally with a single dose of 20 Gray (Gy) when the tumor reached a size of about 100 mm3 (around day 4)." (PMID 25985209, 2015). "Novel associations between TMPRSS2-ERG and alterations in the tumor stroma, for example, increased vascular density, hyaluronan and PDGFRβ and decreased Caveolin-1, all known to be associated with an aggressive disease, were found." (PMID 24505269, 2014). "Stromal Cav-1 loss is highly correlated with conventional tumor markers and HER-2/neu amplification." (PMID 24949874, 2014). "The autophagic tumor stroma model of cancer metabolism suggests that the loss of stromal Cav-1 as a key regulator is a potential therapy target, further suggesting that stromal Cav-1 expression in stromal cells can be of prognostic significance." (PMID 24949874, 2014). "As an adhesion molecule, CD147 mediates molecular events by interacting with a wide range of tumor and inflammation-associated molecules including integrins, monocarboxylate transporters (MCTs), cyclophilins, caveolin-1, and E-selectin." (PMID 24739808, 2014). "The loss of stromal Cav-1 was correlated with the amplification of classic markers for tumor progression (HER-2/neu gene)." (PMID 24949874, 2014). "Caveolin-1 has been found to be highly expressed in some tumors in vivo and associated with increased tumor-cell survival, aggressiveness, metastatic potential, and suppression of apoptosis." (PMID 25243186, 2014). "Owing to the autophagic tumor stroma model of cancer metabolism, the loss of Cav-1 protein likely affects tumor progression via metabolism transform, which is worthy of further study." (PMID 24949874, 2014). "Immunohistochemical analysis of NSCLC detected caveolin-1 expression in 15-30% of specimens and the loss of the caveolin-1 expression correlated with tumor progression, poor prognosis and drug resistance." (PMID 24533441, 2014). "This review summarizes the novel data concerning the clinical values and probable mechanisms of Cav-1 expression in tumor stromal (predominantly in cancer-associated fibroblasts) and cancer cells, respectively." (PMID 25202343, 2014).